DRD4 (dopamine receptor D4)
Diseases named in the same sentence as DRD4 in open-access papers (continued):
Sharing a sentence is not in itself a finding about the gene and the disease.
Parkinson disease (9 papers, 2008 to 2025). A progressive degenerative disorder of the central nervous system characterized by loss of dopamine producing neurons in the substantia nigra and the presence of Lewy bodies in the substantia nigra and locus coeruleus. "Our study suggests that the DRD4 7+ polymorphism is associated with a specific ICD phenotype characterized by the presence of severe social consequences in Parkinson's patients treated with DA." (PMID 38952083, 2024). "In this retrospective study, we analyzed a cohort of Parkinson's disease patients treated with dopamine agonists and investigated the influence of the dopamine D4 receptor gene polymorphism, DRD4 7R+, which is linked to psychiatric disorders, impulsive traits, and addictive behaviors." (PMID 38952083, 2024). "Wan conducted experiments to test the hypothesis that the DRD4 polymorphism is associated with the susceptibility to Parkinson’s disease." (PMID 29422030, 2018). "Previous studies also found the role of EZH2 for DNA hypermethylation in the epigenetic inhibition of the dopamine receptor D4 (DRD4), which is important for neurodegenerative disease such as HD and Parkinson’s disease." (PMID 26636336, 2015). "In these regions, the DRD4 protein acts as a regulator of dopamine levels, where mis-expression of DRD4 has also been associated with the onset of cognitive, behavioural and personality disorders e.g., shyness, ADHD, addiction and Parkinson's disease." (PMID 21599953, 2011). "For example, by searching mouseNET with a set of genes (Mapt, Sncaip, Tbp, Drd4, Ndufv2 and Nr4a2) already known to be involved in Parkinson's disease, we are able to extract other genes annotated to this disease and some novel candidates." (PMID 18818725, 2008). "Of note, in the healthy human substantia nigra, DRD1, DRD3, DRD4, and DRD5 did not exhibit an expression pattern opposite to that of the Parkinson's disease‐associated molecule SNCA." (PMID 41249856, 2025).
glioblastoma (8 papers, 2017 to 2025). The most malignant astrocytic tumor (WHO grade IV). "According to research findings, high level of DRD4 expression has worse survival than low of DRD4 expression in Glioblastomas." (PMID 34906147, 2021). "DRD4 plays a role in tumorigenicity and metastasis of glioblastoma." (PMID 36345155, 2023). "In glioblastoma, DRD4 could promote proliferation and autophagic flux and enhance survival of glioblastoma stem cells." (PMID 34291083, 2021).
psychosis (8 papers, 2012 to 2024). "The DRD4 Ex3 polymorphism s alleles were more common for depressive episode, dysthymia, and psychotic disorders as well as generalized anxiety disorder." (PMID 33171585, 2020). "In the DRD4 Ex3 gene polymorphism for the s/s genotype, psychotic disorders and generalized anxiety were more common, while for the s/l and l/l genotype, they were less frequent." (PMID 33171585, 2020). "In our study, in the DRD4 Ex3 gene polymorphism for the s/s genotype, psychotic disorders and generalized anxiety were more common, while for the s/l and l/l genotype, they were less frequent." (PMID 33171585, 2020). "The DRD4 Ex3 polymorphism s alleles were more common for depressive episode, dysthymia, psychotic disorders, and generalized anxiety disorder." (PMID 33171585, 2020). "Chromosome 11 includes several plausible candidate genes for major psychiatric disorders, especially psychosis, including the tyrosine hydroxylase (TH) and the dopamine receptor D4 (DRD4) (both at 11p15)." (PMID 23300629, 2012). "Our data challenged the hypothesis of the therapeutic benefits of DRD4 agonists, pointing out a possible aggravation of psychosis." (PMID 36854793, 2023). "Our results do not contradict the use of DRD4 mRNA levels as a marker of the predisposition to psychosis (schizotypy)." (PMID 29221470, 2017). "In contrast, DRD1 and 5HTR2C were DEGs for the psychosis and agitation domains while the psychosis domain also demonstrated DRD2 and DRD4 as DEGs." (PMID 38575567, 2024). "Disturbed dopamine function is important for psychosis, and most antipsychotic treatments target DRD2-like dopamine receptors (DRD2, DRD3, DRD4)." (PMID 37031222, 2023).
conduct disorder (7 papers, 2007 to 2025). A disorder diagnosed in childhood or adolescence age group characterized by aggressive behavior, deceitfulness, destruction of property or violation of rules that is persistent and repetitive, and within a one year period. "The results suggest that a gene × gene interaction between DRD2 and DRD4 is associated with the development of conduct disorder and adult antisocial behavior in males." (PMID 17587443, 2007). "In this study, we test whether DRD2 and DRD4 are associated with multiple measures of conduct disorder and with a measure of antisocial behavior." (PMID 17587443, 2007). "Carriers of at least one allele containing seven repeats (DRD4-7R), whose mothers indicated a state of increased stress during pregnancy using the questionnaire method, were found to be at increased risk for a diagnosis of conduct disorder and/or oppositional defiant disorder." (PMID 40943571, 2025). "The connections between ADHD and oppositional defiant disorder/conduct disorder are complex, involving shared genes like the dopamine receptor D4 (DRD4) gene, and environmental conditions such as family dysfunction." (PMID 39752340, 2025). "An interaction has been reported between SoB and the expression of the DRD4 48 bp VNTR in children with hyperkinetic disorder comorbid with conduct disorder as well as in controls, which differ significantly from each other." (PMID 21072167, 2010). "This study examined whether adolescent conduct disorder and adult antisocial behavior were related to the dopamine D2 receptor polymorphism (DRD2) and the dopamine D4 receptor polymorphism (DRD4)." (PMID 17587443, 2007). "However, DRD2 interacted with DRD4 to predict variation in adolescent conduct disorder and in adult antisocial behavior." (PMID 17587443, 2007). "Non-winter born children carrying the DRD4 48 bp VNTR 7-repeat allele showed higher levels of susceptibility to risk of developing hyperkinetic disorder and conduct disorder." (PMID 21072167, 2010). "The left hand side of the table reveals that DRD2 has a marginally significant effect on conduct disorder (b = .141, p = .059), whereas DRD4 does not exert an independent effect on the wave 1 conduct disorder scale (b = .036, p = .656)." (PMID 17587443, 2007). "Multivariate regression analysis revealed that neither DRD2 nor DRD4 had significant independent effects on conduct disorder or antisocial behavior." (PMID 17587443, 2007). "Over the last decade, several candidate genes (i.e., MAOA, DRD4, DRD2, DAT1, 5-HTTLPR, and COMT) have been extensively studied as potential moderators of the detrimental effects of postnatal family adversity on child externalizing behaviors, such as aggression and conduct disorder." (PMID 26537239, 2015).
eating disorder (6 papers, 2014 to 2025). A broad group of psychological disorders with abnormal eating behaviors leading to physiological effects from overeating or insufficient food intake. "A significant association was also found between eating disorder scores and DRD4 rs1800955 (F[1, 4972] = 9.184, p = 0.0025, Cohen’s d = 0.09), where the minor allele was associated with lower mean scores on the EAI (0.67 ± 0.92, n = 2298) as compared to the major (T) allele (0.76 ± 0.98, n = 2676)." (PMID 35629112, 2022). "Finally, we found an association between rs1800955 of the DRD4 gene and the mean scores on the SCOFF questionnaire assessing eating disorders." (PMID 35629112, 2022). "In particular, the dopamine receptor D4 (DRD4) has been identified to be involved in the modulation of the reward process of PF consumption and may contribute to the dysregulation of food intake in patients with eating disorders." (PMID 40365131, 2025). "Furthermore, DRD4 has been identified to be involved in the modulation of the reward process of PF consumption and may contribute to the dysregulation of food intake in patients with eating disorders." (PMID 40365131, 2025).
mood disorder (6 papers, 2015 to 2025). A cognitive disorder a disturbance in which the person's mood is hypothesized to be the main underlying feature. "When comparing the group of patients with mood disorders separately to the control group, associations were detected only for one genetic variant—rs1800955 (DRD4 gene)." (PMID 38397229, 2024). "Along with that, an association of rs1800955 in DRD4 with mood disorders and delusions was also demonstrated." (PMID 38397229, 2024). "Rightward parietal asymmetry (RPA) was associated with carrying the DRD4-7R risk allele, being male, having mood disorder, and having anxiety disorder." (PMID 25999865, 2015). "Another study performed by the same authors showed that functional variants in the DRD4 gene may be associated with delusional symptoms in mood disorders." (PMID 38397229, 2024). "In the cluster, particular attention was given to investigating the risk posed by dopamine receptors genes (i.e., DRD1, DRD2, DRD3, and DRD4) in the development of mood disorders." (PMID 36833279, 2023). "The link between dopamine receptor D4 gene and delusions in mood disorders was also supported by further works." (PMID 36833279, 2023).
nicotine addiction (6 papers, 2004 to 2022). "Finally, the relationship between the IRS group endophenotype and other genetic polymorphisms related to the brain’s reward system and nicotine dependence should be examined, including dopamine D4 receptor (DRD4) and DA transporter (SLC6A3) genes." (PMID 24065931, 2013). "The aim of this study was to identify the genetic variants in the DRD4 and HTR2A genes that are associated with cigarette smoking and a higher degree of nicotine addiction in the Mexican Mestizo population." (PMID 28103253, 2017). "Among Mexican mestizos, the C allele of rs1800955 in the DRD4 gene and the A allele of rs6311 in the HTR2A gene are associated with cigarette smoking, whereas the T allele of rs6313 in HTR2A is associated with cigarette smoking and the degree of nicotine addiction." (PMID 28103253, 2017). "There are differences in the genotype frequencies of SNPs in genes related to nicotine metabolism (CYP2A6) and nicotine dependence (NRXN1, DRD4, CHRNA3-CHRNA5)." (PMID 34205269, 2021). "It is important to evaluate the role of the DRD4 gene in the mechanism of nicotine addiction; however, it is also necessary to consider, in addition to SNP and VNTR polymorphisms, other mechanisms which could participate in the risk of nicotine addiction, such as epigenetic factors." (PMID 31905892, 2019). "Previously, we had reported other SNPs in smoking-related genes as NRXN1, DRD4, HTR2A, CHRNA3, CHRNA5, and CYP2A6 in Mexican mestizo, focused on smokers enrolled in a smoking cessation program, mostly with high tobacco consumption and nicotine dependence." (PMID 34205269, 2021). "No main effect of DRD4 on novelty seeking, nicotine dependence, smoking history or response to smoking cues." (PMID 19570274, 2004).
cognitive deficits (5 papers, 2015 to 2023). "Methylation of the promoter of dopamine receptor genes (DRD2, DRD3, and DRD4) also alters dopamine expression and causes cognitive deficits associated with SCZ." (PMID 36406755, 2022). "In accordance with our results, it has been reported that DRD1, DRD2, DRD3, DRD4, and SLC2A9 are associated with cognitive performance or cognitive impairment." (PMID 34285142, 2021). "The genes of cognitive impairment modified by DNA methylation include GAD1, BDNF, DRD3, DRD4, and 5HTR1A." (PMID 36406755, 2022).
mental disorder (5 papers, 2018 to 2024). A disease that has its basis in the disruption of mental process. "The limited pool of data on DRD4 rs10800955 effects indicates the need to further investigate the genetic variant association with mental disorders." (PMID 38397229, 2024). "Significant associations between rs6265 BDNF and rs1800955 DRD4 and mental impairments were detected when comparing the general group of patients with mental disorders (without separation into diagnoses) to the control group." (PMID 38397229, 2024). "In our results, therapeutic targets or biomarkers of neurological disorder and mental disorder, such as DRD1, DRD2, DRD4, HTR2A, PRL and ADRA2A, were assigned with high scores in both mirtazapine and pramipexole." (PMID 29371651, 2018). "The effect of BDNF rs10835210 and DRD4 rs1800955 on mental disorder development was not investigated in the ethnic Russian population." (PMID 38397229, 2024).
migraine (5 papers, 2009 to 2024). "Also reports in the literature exist that migraineurs have an increased density of dopamine receptors DRD3 and DRD4 on lymphocytes and that DA agonists can bring about migraine." (PMID 24403849, 2013). "Subsequent studies found association between migraine phenotypes and polymorphisms in DRD4 and DBH, although negative associations have also been described." (PMID 19772578, 2009).
adenoma (3 papers, 2018 to 2025). A neoplasm arising from the epithelium. "DRD4 staining progressively intensified from normal tissues to adenomas, adenocarcinomas, and liver metastases." (PMID 39679842, 2025). "Interestingly, DRD4 expression was also significantly elevated in colorectal polyps, adenomas, and adenocarcinomas, as analyzed through the GEO databases GSE128435 and GSE41657." (PMID 39679842, 2025). "The statistical analysis results revealed that DRD4 expression was significantly higher in CRC tissues compared to 79 paired normal tissues and 30 paired adenoma tissues individually, and further increased in distant metastases." (PMID 39679842, 2025). "Nevertheless, the analysis of DRD4 and DRD5 expression may serve as a potential prognostic tool for GH‐producing adenomas." (PMID 29266696, 2018). "However, the molecular study revealed, for the first time, that although the expression of sst3, DRD4 and DRD5 is low in these samples, it is increased in adenomas with suprasellar extension compared with the tumours with no suprasellar growth." (PMID 29670116, 2018).
dependence (3 papers, 2013 to 2021). "Association of genetic polymorphism of COMT and DRD4 genes with a risk of specific drug dependence." (PMID 33544778, 2021). "The subtelomeric region of chromosome 11p–where the DRD4 gene is located - was identified in a genome-wide search for quantitative trait loci influencing substance dependence vulnerability." (PMID 23840506, 2013). "Nonetheless, twelve genes contained three or more DM loci, including several genes previously involved in studies of alcohol exposure and dependence, but not present in the Phenocarta list, such as SLC6A3 and DRD4." (PMID 27358653, 2016).
diabetes (3 papers, 2024 to 2025). "To confirm this, we then analyzed several known clock-controlled genes for the retina (Adcy1, Drd4, Nr2e3, Cys1, Plekbh1, Usp2) that also showed amplitude changes but no phase changes, indicating that the retinal clock was entrained to the 12L:12D cycle at this stage of diabetes." (PMID 38039846, 2024).
dyslexia (3 papers, 2012 to 2023). A learning disorder characterized by an impairment in processing written words. "Besides, a dyslexia susceptibility locus (DYX7) has been identified to link to dopamine D4 receptor (DRD4) region on chromosome 11p15.5 in participants of European ancestry." (PMID 25178928, 2014). "Among the top 20 genes with the highest priority DRD2, DRD4, CNTNAP2 and GRIN2B are mentioned in the literature as directly linked with the comorbidity of ADHD and dyslexia." (PMID 37667328, 2023). "Other frequent susceptibility genes for ADHD and dyslexia include DYX1C1 and DRD4." (PMID 37667328, 2023). "The DYX7 locus on chromosome 11p15 was found by a targeted study of the dopamine receptor D4 (DRD4) as a candidate for dyslexia based on its postulated involvement in Attention deficit/hyperactivity disorder (ADHD) and the frequent co-occurrence of the two disorders." (PMID 23308072, 2012).
heroin dependence (3 papers, 2013 to 2023). Physical and psychological dependence on the drug heroin. "An additional interesting finding of the network analysis is the effect of another DRD4 promoter polymorphism (−615 A/G), which has an indirect effect on our target variable (heroin dependence)." (PMID 23840506, 2013). "Moreover, the –521 C/T polymorphism of the DRD4 gene and heroin dependence also showed a nominal association (p = 0.007)." (PMID 23840506, 2013). "As a result, the applied Bayesian method confirmed the relevance of DRD2 TaqIB SNP in heroin dependence and revealed a new interaction partner in the DRD4 promoter, the −615 A/G SNP modulating through the −521 C/T SNP." (PMID 23840506, 2013).
lung cancer (3 papers, 2021 to 2025). A malignant neoplasm involving the lung. "Besides, DRD4, ZNF132 and ZNF43 have been linked with other non-lung cancer types: DRD4, encoding dopamine receptor, is involved in early brain development and epigenetically repressed in pediatric CNS tumors; it also has be identified as a potential epidriver in hepatocellular carcinoma." (PMID 35313869, 2022). "We reported the first clinical evidence that methylation of DRD4, ZNF132 and ZNF43t may be also involved in lung cancer development." (PMID 35313869, 2022). "The expression levels of DRD4 (control, free BRC, and MWCNTs-BRC Nf) in cancer cell lines were higher significantly compared to MRC5 groups, and the expression levels of DRD4 were significantly higher in QU-DB lung cancer cell lines compared to A549 cell lines." (PMID 34952904, 2021).
pancreatic cancer (3 papers, 2022 to 2025). "Accordingly, the same authors have shown that DRD4 signalling on macrophages improves the efficacy of gemcitabine chemotherapy in mouse models of pancreatic cancer." (PMID 36428964, 2022).
retinoblastoma (3 papers, 2005 to 2022). A malignant tumor that originates in the nuclear layer of the retina. "It has been reported in a human retinoblastoma cell line that the -521C>T SNP has significant influence on the transcriptional efficiency of the DRD4 gene suggesting the relevance of a single SNP in dopaminergic neurotransmission." (PMID 15985158, 2005). "Significant expression of the DRD4 gene was demonstrated in SK-N-F1 and IMR32 neuroblastoma cells, as well as in Y79 retinoblastoma cell line." (PMID 16723017, 2006). "Endogenous mRNA expression of the DRD4 gene was demonstrated in two neuroblastoma (SK-N-F1, IMR32) and one retinoblastoma cell line (Y79) by RT-PCR." (PMID 16723017, 2006).
alcohol addiction (2 papers, 2023 to 2024). "In males, factors exhibiting significant alcohol addiction risk included CHRNB3 (OR 2.35, p < 0.001), DRD4 (OR 1.84, p = 0.018), and CHRNB3_ZBTB20 (OR 3.19, p = 0.018)." (PMID 39766481, 2024).
behavior problems (2 papers, 2016 to 2018). "We observed a significant interaction of child DRD4 7R allele carrier genotype and low maternal sensitivity (assessed by laboratory observation of mother-infant interactions at 6 months) that predicted child externalizing behavior problems at 18 months." (PMID 27494520, 2016). "Replication Analysis: Linear regression of effect of DRD4 genotype, maternal sensitivity, and their interaction on 18 month child Externalizing Behavioral problems (Achenbach CBCL)§." (PMID 27494520, 2016). "A 63 family sample with data for observed maternal sensitivity ratings, DRD4 VNTR genotype, and maternal report of child behavior problems at 18-months was used in this preliminary analysis." (PMID 27494520, 2016).
colorectal cancer (2 papers, 2021 to 2025). A primary or metastatic malignant neoplasm that affects the colon or rectum. "This study identifies an unconventional role of dopamine receptor D4 (DRD4) in colorectal cancer (CRC), revealing its overexpression correlates with poor prognosis." (PMID 39679842, 2025). "However, the roles of DRD4 in colorectal cancer (CRC) remain unclear." (PMID 39679842, 2025).